UBR2 (ubiquitin protein ligase E3 component n-recognin 2)
Description:
E3 ubiquitin-protein ligase which is a component of the N-end rule pathway. Recognizes and binds to proteins bearing specific N-terminal residues (N-degrons) that are destabilizing according to the N-end rule, leading to their ubiquitination and subsequent degradation. Recognizes both type-1 and type-2 N-degrons, containing positively charged amino acids (Arg, Lys and His) and bulky and hydrophobic amino acids, respectively. Does not ubiquitinate proteins that are acetylated at the N-terminus. In contrast, it strongly binds methylated N-degrons. Plays a critical role in chromatin inactivation and chromosome-wide transcriptional silencing during meiosis via ubiquitination of histone H2A (By similarity). Binds leucine and is a negative regulator of the leucine-mTOR signaling pathway, thereby controlling cell growth. Required for spermatogenesis, promotes, with Tex19.1, SPO11-dependent recombination foci to accumulate and drive robust homologous chromosome synapsis (By similarity). Polyubiquitinates LINE-1 retrotransposon encoded, LIRE1, which induces degradation, inhibiting LINE-1 retrotransposon mobilization (By similarity). Catalyzes ubiquitination and degradation of the N-terminal part of NLRP1 following NLRP1 activation by pathogens and other damage-associated signals: ubiquitination promotes degradation of the N-terminal part and subsequent release of the cleaved C-terminal part of NLRP1, which polymerizes and forms the NLRP1 inflammasome followed by host cell pyroptosis (By similarity). Plays a role in T-cell receptor signaling by inducing 'Lys-63'-linked ubiquitination of lymphocyte cell-specific kinase LCK. This activity is regulated by DUSP22, which induces 'Lys-48'-linked ubiquitination of UBR2, leading to its proteasomal degradation by SCF E3 ubiquitin-protein ligase complex.
Synonyms: C6orf133; KIAA0349; bA49A4.1; dJ392M17.3; dJ242G1.1
Tractability: Antibody: the Human Protein Atlas places it where antibodies can reach. PROTAC: UniProt records ubiquitination sites on it; ubiquitination databases record sites on it; its protein half-life has been measured.
Target class: Enzyme; Transferase
Gene: Protein-coding gene on chromosome 6 (42,563,995 to 42,693,505, forward strand). Ensembl gene ENSG00000024048.
Subcellular location: Nucleus; Chromosome
Subcellular location (Human Protein Atlas): Nucleoplasm; Plasma membrane
Pathways (Reactome):
Immune System: Antigen processing: Ubiquitination & Proteasome degradation
Gene Ontology:
Molecular function: L-leucine binding; protein binding; ubiquitin protein ligase activity; histone H2A ubiquitin ligase activity; zinc ion binding
Biological process: cellular response to L-leucine; negative regulation of TOR signaling; positive regulation of T cell receptor signaling pathway; proteasome-mediated ubiquitin-dependent protein catabolic process; protein K63-linked ubiquitination; ubiquitin-dependent protein catabolic process via the N-end rule pathway; heterochromatin formation; male meiotic nuclear division; protein ubiquitination; reciprocal meiotic recombination; spermatogenesis; transposable element silencing; protein catabolic process
Cellular component: chromosome; cytoplasm; cytosol; nucleus; ubiquitin ligase complex; chromatin
Genetic constraint (gnomAD): Loss-of-function variants: 75 observed, 192.54 expected, observed/expected ratio (o/e) 0.39, 90% interval 0.32 to 0.47. The upper end of that interval is the gene's LOEUF score, 0.47, which puts it in group 2 of 6, group 1 being the genes least tolerant of losing a copy. Missense variants: 1,428 observed, 1,923.7 expected, observed/expected ratio (o/e) 0.74, 90% interval 0.71 to 0.77. Synonymous variants: 595 observed, 641.65 expected, observed/expected ratio (o/e) 0.93, 90% interval 0.87 to 0.99.
Homologues: Orthologues: macaque UBR2 (99% identical), chimpanzee UBR2 (99% identical), dog UBR2 (96% identical), pig UBR2 (94% identical), guinea pig UBR2 (94% identical), rabbit UBR2 (94% identical), rat Ubr2 (90% identical), mouse Ubr2 (90% identical), tropical clawed frog ubr2 (81% identical), zebrafish ubr2 (72% identical), Drosophila melanogaster Ubr1 (34% identical), Caenorhabditis elegans ubr-1 (29% identical). Paralogues in human: UBR1 (47% identical), UBR3 (22% identical).
Diseases named in the same sentence as UBR2 in open-access papers:
UBR2 is named in the same sentence as 23 diseases in open-access papers, as found by Europe PMC text mining. Sharing a sentence is not in itself a finding about the gene and the disease. The quoted sentences say what the papers report.
gastric cancer (9 papers, 2019 to 2023). A primary or metastatic malignant neoplasm involving the stomach. "Despite the small amount of studies on exosomes, UBR2 and GC, exosomal UBR2 remains linked to stomach cancer." (PMID 35066729, 2023). "Similarly, BM-MSC-EVs can deliver ubiquitin protein ligase E3 component n-recognin 2, which has proliferative and migratory effects on gastric cancer cells." (PMID 31547882, 2019).
autoimmune pancreatitis (2 papers, 2013 to 2024). "It was also reported that the peptide homologous to UBR2 (ubiquitin-protein ligase E3 component n-recognin 2), which is an enzyme highly expressed in pancreatic acinar cells, was also the target antigen of autoantibody detected in the serum of patients suffering from autoimmune pancreatitis." (PMID 23991207, 2013).
breast carcinoma (2 papers, 2020 to 2026). "UBR2 is widely expressed in a variety of human cancer tissues, particularly breast cancer, prostate cancer, and lymphomas." (PMID 41344988, 2026). "We observed that UBR2 is widely expressed among different human cancer tissues, especially in lymphomas, prostate, and breast cancer." (PMID 33288741, 2020). "We observed that independent breast cancer cell lines presented variable amount of UBR2 protein expression, with the highest expression in MDA-MB-231 breast cancer cells." (PMID 33288741, 2020). "We then observed that UBR2 is overexpressed in several cancers, especially in breast cancers and contributes to CICD resistance." (PMID 33288741, 2020). "This is supported by the observation that breast cancer patients with higher UBR2 expression have a poor survival compared to patients with low UBR2 expression upon treatment." (PMID 33288741, 2020). "Collectively, these data suggest that UBR2 is overexpressed in cancer cells, especially in breast cancer and that it could participate to CICD resistance." (PMID 33288741, 2020). "Also, we showed that overexpression of UBR2 protects cells against CICD and that UBR2 is found overexpressed in many types of cancer including breast cancers." (PMID 33288741, 2020). "Interestingly, UBR2 knock-down breast cancer cells are more sensitive to CICD than control cells, suggesting that overexpression of UBR2 in MDA-MB-231 cells could participate to the escape from CICD." (PMID 33288741, 2020).
infertile (2 papers, 2012 to 2022). "The infertility likely results from UBR2 histone ubiquitination insufficiency triggering the pachytene checkpoint system." (PMID 35286314, 2022). "In contrast to 129/C57 UBR2−/− mice which show male-specific infertility, as genetic background shifted toward C57 background, UBR2 knockout caused neonatal lethality apparently in both males and females." (PMID 22616001, 2012). "To characterize the role of UBR2 in mammalian development outside infertility, we generated UBR2−/− mice enriched in the C57 background by backcrossing UBR2+/− mice in C57/129 mixed background into C57BL/6 background for more than eight generations." (PMID 22616001, 2012). "Male mice lacking UBR2 are infertile associated with arrest at meiotic prophase I and germ cell apoptosis, whereas the majority of UBR2−/− females die throughout development." (PMID 22616001, 2012).
leukemia (2 papers, 2023 to 2025). A malignant (clonal) hematologic disorder, involving hematopoietic stem cells and characterized by the presence of primitive or atypical myeloid or lymphoid cells in the bone marrow and the blood. "Transduction of UBR1 and UBR2 was sufficient to rescue leukemia cells from shSOD2-mediated sensitization to asparaginase while transduction of FBXW7 or STUB1 could not reverse this effect." (PMID 40131931, 2025). "Besides Mecom, other integrations near or within leukemia-related proto-oncogenes or tumor suppressors were found within the top 10 most abundant in the expanded clones (Anxa659, Nemf or Sdccag1, Ldhc, Nbea, Rap1gap2, Iqgab1, Cript, Kalrn, Pkig, and Ubr2)." (PMID 37566057, 2023).
pancreatic cancer (2 papers, 2011 to 2024). "Exosomes from pancreatic cancer cells reduced myosin heavy chain (MHC) expression by activating the P38/CEBPβ/UBR2/Atrogin1 signaling pathway in skeletal muscle cells, leading to muscular duct atrophy and muscle weight loss in the cachexia model of mice with in situ pancreatic cancer." (PMID 38689293, 2024).
autoimmune disease (1 paper, 2024). A disorder resulting from loss of function or tissue destruction of an organ or multiple organs, arising from humoral or cellular immune responses of the individual to their own tissue constituents. "Our findings on the regulation of Lck activation by UBR2 may provide therapeutic approaches to treat autoimmune diseases." (PMID 38225265, 2024). "Taken together, UBR2-induced Lck trans-autophosphorylation and Lys63-linked ubiquitination were further enhanced by DUSP22 deficiency, leading to proinflammatory cytokines production and autoimmune disease." (PMID 38225265, 2024). "Thus, our mechanistic insights on Lck activation and inactivation by UBR2 and DUSP22, respectively, may provide therapeutic strategies to reduce T-cell-mediated autoimmune disease." (PMID 38225265, 2024).
Cachexia (1 paper, 2020). Severe weight loss, wasting of muscle, loss of appetite, and general debility related to a chronic disease. "The Zip4-related cachexia was attributed to increased expression of Atrogin1 and another ubiquitin E3 ligase, Ubr2." (PMID 32132660, 2020).
chronic myeloid leukemia (1 paper, 2018). "Remarkably, previous studies also showed that the proteolytically-generated anti-apoptotic Lyn kinase protein fragment is targeted for degradation by the UBR1/UBR2 E3 ubiquitin ligases of the N-end rule pathway in chronic myeloid leukemia cells." (PMID 30384441, 2018).
Fanconi anemia (1 paper, 2012). Fanconi anemia (FA) is a hereditary DNA repair disorder characterized by progressive pancytopenia with bone marrow failure, variable congenital malformations and predisposition to develop hematological or solid tumors. "In addition, pachytene-like UBR2−/− spermatocytes showed a normal staining pattern for FANCD2, a component of the Fanconi anemia (FA) complex, whose monoubiquitylation is a hallmark for recruitment of FA components and other repair proteins." (PMID 22616001, 2012).
Obesity (1 paper, 2021). Accumulation of substantial excess body fat. "SNVs in QSER1 and UBR2 has been previously linked with neurodegenerative (Parkinson’s) disease and obesity, respectively." (PMID 34385509, 2021).
cancer (10 papers, 2014 to 2026). A tumor composed of atypical neoplastic, often pleomorphic cells that invade other tissues. "Muscle-specific E3 ubiquitin ligases MuRF-1, UBR2 (also known as E3α-II), and atrogin-1 play a key role in mediating the degradation of muscle proteins in cancer cachexia." (PMID 36471329, 2022). "UBR2 is a RING E3 ligase that belongs to the N-End rule pathway, is implicated in spermatogenesis and can be up-regulated during cancer and cachexia, promoting tumor growth and metastasis." (PMID 33288741, 2020). "Collectively, these data suggest that UBR2 can protect cancer cells from CICD through the activation of the prosurvival MAPK/Erk signaling pathway." (PMID 33288741, 2020). "On balance, these findings are consistent with the hypothesis that SOD2 regulates cancer cell survival during amino acid starvation by its interaction with UBR2." (PMID 40131931, 2025). "UBR2 was upregulated through the p38β MAPK–C/EBPβ (CCAAT/ enhancer binding protein beta) signaling pathway and caused selective degradation of MHC, particularly in fast-twitch muscle as a mechanism towards establishing cachexia in diverse cancer types." (PMID 36831310, 2023). "A similar UBR2-regulated mechanism was found to be conserved in humans, as part of the observation from mice was also validated in rectus abdominis skeletal muscle isolated from early stage of human cancer patients." (PMID 36831310, 2023). "Cancer-upregulated E3 ligase UBR2 plays a critical role in cachexia by targeting the fast-twitch muscle fiber isoforms MHC II-b and II-x for proteasomal degradation, resulting in loss of contractile function in fast fibers, which contributes to cancer cachexia." (PMID 40759570, 2025). "Murine Tex19.1 interacts with the E3 ubiquitin ligase Ubr2 which contains a nuclear localization signal, so a role for a UBR2-TEX19 interaction in human cancers would be worthy of further investigation." (PMID 28446200, 2017). "Therefore, our work defines UBR2 as a novel regulator of CICD, found overexpressed in cancer cells, suggesting that its targeting may represent an innovative way to kill tumor cells." (PMID 33288741, 2020).
tumor (6 papers, 2017 to 2022). "The p38β MAPK–C/EBPβ signaling pathway also mediates the upregulation of the E3 ligase UBR2 in cachectic muscle of LLC tumor-bearing mice." (PMID 31480237, 2019). "We also show that MBT-2 tumor-derived CM upregulated the expression of atrophy-related E3 ubiquitin ligases MuRF-1, UBR2, and atrogin-1 in C2C12 cells, which could be downregulated by Hotair knockdown." (PMID 36471329, 2022). "In addition, UBR2 is upregulated in C26 tumor-bearing mice and YAH-130 tumor-bearing rats, suggesting a role for this E3 in muscle catabolism induced by diverse types of cancer." (PMID 31480237, 2019).
UBR2 also shares sentences with these, for which no sentence is quoted: infection (3 papers); lymphoma (2); Azoospermia (1); bladder cancer (1); experimental autoimmune encephalomyelitis (1); IgG4-related pancreatitis (1); Parkinson disease (1); prostate carcinoma (1); retinal dystrophies (1); stomach cancer (1).